RNU6-1205P (RNA, U6 small nuclear 1205, pseudogene)
Gene: Small nuclear RNA gene on chromosome 1 (248,912,690 to 248,912,795, reverse strand). Ensembl gene ENSG00000200495.
Homologues: Orthologues: chimpanzee U6 (97% identical), macaque U6 (90% identical), dog U6 (78% identical). Paralogues in human: RNU6-11P (87% identical), RNU6-37P (87% identical), RNU6-43P (87% identical), RNU6-21P (86% identical), RNU6-25P (86% identical), RNU6-38P (86% identical), RNU6-574P (86% identical), RNU6-97P (86% identical), RNU6-1 (85% identical), RNU6-15P (85% identical), RNU6-2 (85% identical), RNU6-20P (85% identical), and 1288 more.